FAAH (fatty acid amide hydrolase)
Diseases named in the same sentence as FAAH in open-access papers (continued):
Sharing a sentence is not in itself a finding about the gene and the disease.
cancer (continued). "The direct involvement in cancer of enzymes involved in synthesis and degradation of the endogenous ligands has been confirmed by several studies that reported the up-regulated expression of NAAA, MAGL, and FAAH in different cancers." (PMID 31979368, 2020). "Consistent with findings demonstrating that FAAH is overexpressed in cancer, in vitro and in vivo studies revealed that the antitumor activity of endocannabinoids was increased by inhibiting FAAH activity." (PMID 29066974, 2017). "In past years, FAAH inhibitor-induced endo-cannabinoid levels were shown to block cancer cell proliferation, including colorectal cancer cells or to inhibit cancer growth in vitro and in vivo, e.g. of rat thyroid-transformed cells (KiMol)." (PMID 26930716, 2016). "So far, FAAH antagonists have been considered as potential treatments for cancer pain in rodent models, but their potential effects on tumor growth and the anti-tumoral immune response have not been assessed." (PMID 26875980, 2016). "All of these eCBs are primarily metabolized by fatty acid amide hydrolase (FAAH) which is upregulated in various types of cancer, suggesting that enhanced degradation contributes to the loss of production by normal cells." (PMID 26875980, 2016). "Fatty Acid Amide Hydrolase (FAAH)—an upregulated serine hydrolase in tumors—regulates cancer proliferation, and its inhibitors exhibit anti-invasive/anti-metastatic effects, often synergizing with chemotherapeutics; importantly, FAAH inhibitors are well-tolerated in clinical trials." (PMID 41425591, 2025). "FAAH, a member of the serine hydrolase family, was initially identified as a major catabolic enzyme that regulates various metabolic pathways and pathophysiological processes, including cancer cell proliferation." (PMID 39335103, 2024). "Among cancer patients, the activity of FAAH was also reported to be upregulated." (PMID 37921652, 2023). "Similarly, FAAH inhibitors can reduce cancer cell growth in vitro and in vivo in mouse xenograft tumor models." (PMID 36834678, 2023). "Therefore, FAAH exhibited a significant cancer-promoting effect, and interference with FAAH in vitro inhibited the malignant phenotype of GC cells." (PMID 36702852, 2023). "Finally, inhibition of FAAH has also been shown to mediate cancer-limiting effects with growth inhibitory as well as anti-invasive and antimetastatic properties." (PMID 35277658, 2022). "In addition, the mRNA levels of NAPE-PLD, FAAH, and ceramide synthases, such as CerS2, CerS5, and CerS6, are higher in cancer tissues." (PMID 34503163, 2021). "Thus, inhibition of the enzymes involved in the biodegradation of the endocannabinoids has been shown to play a role in cancer cell viability, migration, and metastasis, as, for instance, does the FAAH inhibitor URB597 in lung cancer cells." (PMID 31214034, 2019). "Moreover, knockdown of FAAH by siRNA was shown to confer decreased cancer cell invasiveness and increased TIMP-1 expression." (PMID 26930716, 2016). "FAAH has been well characterized over the years and, importantly, it represents a promising drug target to treat several diseases, including inflammatory-related diseases and cancer." (PMID 26111155, 2015). "Inhibitors of FAAH may provide novel options for the treatment of pain, inflammation and cancer, since inhibition of FAAH prolongs and enhances the action of anandamide." (PMID 26712767, 2015). "In addition, an overall decrease in cancer cell FAAH expression was found in a significant proportion of the LN metastases when compared to the corresponding primary tumors, suggesting FAAH downregulation is a frequent event during metastatic progression of luminal BC." (PMID 37253733, 2023). "Therefore, acting simultaneously by inhibiting FAAH and stimulating the activity of PPARs may represent a new approach to cancer therapy." (PMID 38139209, 2023).
cancer (continued). "FAAH is a membrane-bound protein belonging to the serine hydrolase family of enzymes that plays a significant role in the termination of signaling of fatty acid amides (FAAs), a class of bioactive lipids, both in the central nervous system and in some cancer tissues." (PMID 34895237, 2021). "Similarly, it has been proposed that simultaneous inhibition of FAAH and activation of PPARs may have an additive or even synergistic effect in treating cancers, and this approach may similarly hold promise in the context of addiction pharmacotherapy." (PMID 32408505, 2020). "These FAAH/COX inhibitors hold potential as starting points for future drug discovery endeavors targeting pain, inflammation, and cancer." (PMID 40346933, 2025). "FAAH inhibitors promote the endocannabinoid levels of AEA and other fatty acid amides that reduce cancer cell proliferation." (PMID 37921652, 2023). "Further analysis of lipidomics showed that after stable interference with FAAH, the content of AEA increased while cancer-promoting molecules (AA and LPA) decreased, and the content of PE increased while FFA decreased." (PMID 36702852, 2023). "Here, we will mainly discuss changes in FAAH and MAGL expression in cancer and their impact on cancer biology and prognosis." (PMID 36291926, 2022). "In one study, low FAAH and MAGL immunoreactivities in cancer cells were correlated with shorter patient survival." (PMID 34830856, 2021). "This review summarises the relevant preclinical studies with FAAH and MAGL inhibitors compared to studies with cannabinoids and provides an overview of the regulation of the endocannabinoid system in cancer." (PMID 34830856, 2021). "FAAH regulates the levels of its main cannabinoid substrate AEA, and it is overexpressed in different types of cancer." (PMID 29066974, 2017). "Clinical trials with FAAH inhibitors, MAGL inhibitors, CBD, and CBDA are warranted to improve the quality of life of patients undergoing cancer treatment by reducing the side effects of nausea and anticipatory nausea when it develops." (PMID 28861486, 2016). "Our observation of the perfect reversal of the anti-cancer effect of DHEA and NALA by transfecting FAAH into HNSCC cells confirms that DHEA and NALA can be degraded by FAAH." (PMID 27411387, 2016). "In addition, the modulation of the degrading enzymes, FAAH for AEA, and MAGL for 2-AG, appears to play a role in cancer development." (PMID 36834678, 2023). "Therefore, inhibiting the expression of FAAH retained the level of endocannabinoid AEA and reduced the accumulation of FFA, which represents a potential method of treating cancer." (PMID 36702852, 2023). "The preclinical work on the inhibition of FAAH and MAGL in cancer has been summarised elsewhere." (PMID 35277658, 2022). "Interestingly, in both the CNS and in cancer, several components of the ECS were important for CB1/CB2 receptor-independent activity including GRP55, TRP channels, FAAH, and MAGL." (PMID 29066974, 2017). "In addition, FAAH transcripts are present in the EFM-19 and MCF-7 cancer cell lines, as determined by northern blotting and RT-PCR techniques, whilst GPR55 is highly expressed in the MDA-MB-231 and MCF-7 breast cancer cell lines." (PMID 24369462, 2013). "Interestingly, there are no data on the effects of FAAH inhibition on the interaction between cancer cells and endothelial cells, as has been reported for other cannabinoids." (PMID 34830856, 2021). "We hypothesized that other endocannabinoids and structurally similar compounds, which are not substrates for the FAAH, could also induce cancer cell death via GPR55 activation and have no stimulatory effect on cancer cells." (PMID 33435517, 2021). "Interestingly, FAAH and MAGL expression were found upregulated in cancer tissues." (PMID 31979368, 2020). "Also, we utilized tissue microarray (TMA) to detect levels of FAAH and CB1 in cancer patients." (PMID 24811863, 2014).
cancer (continued). "However, given that the FAAH substrates 2-AG and PEA likewise suppressed cancer cell invasion without (PEA) or only weakly (2-AG) increasing TIMP-1 following a 72-h incubation, additional anti-invasive mechanisms of FAAH inhibitors appear feasible." (PMID 26930716, 2016).
tumor (32 papers, 2010 to 2025). "Together, these findings show a strong association between low tumor FAAH expression (either intrinsic or acquired during metastatic progression) and high tumor aggressiveness in BC." (PMID 37253733, 2023). "For example, AA-5HT, another FAAH inhibitor, was described to cause growth inhibition of thyroid cancer xenografts and to reduce tumour development in an in vivo model of colon carcinogenesis." (PMID 34830856, 2021). "Prognostic associations inferred from tumor data including all intrinsic BC subtypes may be biased considering that FAAH has a predominant expression in the luminal subtype of BC, which is the one with the highest inherent survival rates." (PMID 37253733, 2023). "To corroborate the molecular association between FAAH and BC metastasis, we analyzed the mRNA expression of a panel of 84 metastasis-associated genes in MDA-MB-231 parental cells and FAAH-overexpressing MDA-MB-231 cells using the commercial RT2 ProfilerTM PCR Array of Human Tumor Metastasis." (PMID 37253733, 2023). "Interestingly, and in line with our previous observations associating lower FAAH expression to undifferentiated tumor phenotypes, we detected lower FAAH mRNA levels in mammospheres derived from parental T-47D cells than in their adherent, more differentiated counterparts." (PMID 37253733, 2023). "Therapeutic strategies leveraging cannabinoids or cannabinoid-inspired compounds, such as selective agonists or FAAH inhibitors, show promising anti-tumor properties." (PMID 39941074, 2025). "Our experiments in this study preliminarily revealed that FAAH affects tumor-stroma interactions by regulating CCL15 secretion, but the effect of immune cell recruitment needs to be further validated." (PMID 40630945, 2025). "Ultimately, the inhibition of the fatty acid amide hydrolase FAAH is a catabolic enzyme that supports antiproliferative effects on tumor cells via oxidative signals, such as NRF2 activation." (PMID 40076652, 2025). "In GBM, high WWOX/HIF1A conditions leverage FAAH-mediated lipid signalling to resolve inflammation and induce tumour cell death, providing a potential mechanism for immune-mediated tumour suppression." (PMID 41007296, 2025). "In our study, the expression level of FAAH was significantly higher in tumours with chromosomal instability than in normal controls, suggesting a relationship with FAAH-regulated lipid signalling." (PMID 36702852, 2023). "Although tumors formed by MMTV-neu:FAAH−/− showed a delayed tumor onset, they significantly increased their tumor growth rate compared to their FAAH+/+ counterparts, which was accompanied by increased levels of PCNA expression." (PMID 37253733, 2023). "In this study, we detected the expression of FAAH in GC tissues and clarified its effects on tumour progression." (PMID 36702852, 2023). "In the same direction, tumor growth was significantly reduced when xenografts were generated from FAAH-overexpressing MDA-MB-231 cells compared to those generated by the parental cell line." (PMID 37253733, 2023). "IHC staining showed that ki67 staining was attenuated in the LV-shFAAH group, while cleaved caspase-3 staining was enhanced, suggesting that FAAH knockdown reduced tumour proliferation and promoted apoptosis in vivo." (PMID 36702852, 2023). "The expression of GPX4 in tumor tissues was positively correlated with the expression of FAAH (Y = 0.8701*X + 0.16, P < 0.0001)." (PMID 37024452, 2023). "TUNEL immunofluorescence also showed that the apoptosis of tumour cells increased after interference with FAAH." (PMID 36702852, 2023). "On the one hand, silencing of FAAH inhibited the malignant progression of GC in three ways: blocking tumour suppressor signal AEA degradation, providing PE for the synthesis of AEA, and inhibiting downstream AA/COX-2/PGE2 signal activation." (PMID 36702852, 2023).
tumor (continued). "Here, the authors show that fatty acid amide hydrolase is a tumour suppressor for lung metastasis in mouse models of BC and a predictor of metastasis in patients with luminal BC." (PMID 37253733, 2023). "To better understand how FAAH controls tumor progression, we performed a battery of experiments in human cell models of BC." (PMID 37253733, 2023). "Through further analysis, we found that the expression of FAAH in tumours with chromosomal instability (CIN) was significantly different from that in normal tissues." (PMID 36702852, 2023). "Here, we report that the lipid-degrading enzyme fatty acid amide hydrolase (FAAH) is a predictor of long-term survival in patients with luminal BC, and that it blocks tumor progression and lung metastasis in cell and mouse models of BC." (PMID 37253733, 2023). "Further analysis by expanding the sample size indicated that high FAAH expression was significantly related to tumour size, invasion depth, and lymph node metastasis." (PMID 36702852, 2023). "Here, patients with low tumor FAAH expression (scores 0 and 1) had a higher probability for developing distant metastases and a significantly decreased overall survival than patients with high tumor FAAH expression (scores 2 and 3)." (PMID 37253733, 2023). "First, we demonstrate that FAAH is highly expressed in luminal BC, and that its downregulation in the primary tumor and/or LN metastasis is a marker of poor prognosis." (PMID 37253733, 2023). "In order to investigate the potential link between tumor FAAH levels and patient outcomes, we analyzed the clinical data available in the TMA #1." (PMID 37253733, 2023). "On the contrary, in prostate adenocarcinomas biopsies FAAH protein expression increased in comparison to non-tumour biopsies." (PMID 34943903, 2021). "A higher FAAH immunoreactivity is seen in PCa tumour tissue than in the luminal cells in the TINT tissue." (PMID 32286386, 2020). "There was a gradual decrease in levels of FAAH transcript with tumor grade; with the highest levels of 0.445 (0.230–0.720; median and IQR) observed in atrophic endometria (controls)." (PMID 31921630, 2019). "NaGly is produced by many cells and acts as an endogenous inhibitor of FAAH and thereby increases AEA, OEA and PEA levels and counteracts the tumor-mediated loss of these eCBs." (PMID 26875980, 2016). "Up-regulation of FAAH indicates down-regulation of cannabinoids, which play an important role in preventing tumor growth." (PMID 23374458, 2013). "One explanation for the finding that the tumour epithelial FAAH-IR is higher than FAAH-IR in normal prostate epithelial tissue is that a constituent of the tumour microenvironment affects its activity." (PMID 20808855, 2010). "Using this JFAAH, Kaplan-Meier analyses demonstrated a significant contribution of tumour epithelial FAAH-IR upon the disease outcome." (PMID 20808855, 2010). "In contrast, a significant correlation between the tumour CB1IR and the tumour epithelial and blood vessel FAAH-IR was seen." (PMID 20808855, 2010). "The present study shows that in the tumour epithelia, FAAH-IR is correlated with the pEGFR-IR, but that this is secondary to a correlation between CB1IR and pEGFR-IR." (PMID 20808855, 2010). "Here, low FAAH expression in both the primary tumor and the LN samples was associated with lower overall survival, indicating that the prognostic value of FAAH is independent of their association to luminal BC." (PMID 37253733, 2023). "The absence of FAAH in BC cells, either constitutive or induced by genetic silencing, was associated with increased capabilities intimately related to tumor progression such as cell invasion and mammosphere formation." (PMID 37253733, 2023). "We propose that assessing FAAH levels in the tumor may be useful to identify those luminal BC patients that may benefit from more aggressive treatments to decrease the risk of metastatic relapse." (PMID 37253733, 2023).
tumor (continued). "Untreated MKN-1 cells (mock), lentiviral negative control (LV-nc), and MKN-1 cells with stable knockdown of FAAH (LV-shFAAH) were injected into nude mice to construct tumour xenograft models, followed by 5-fluorouracil (5-FU) to act as the control group of chemotherapeutic drugs." (PMID 36702852, 2023). "This implies that FAAH inhibition has to be contextualized based on the tumor type considered to understand what contribution a decrease in its activity may provide." (PMID 38139209, 2023). "This phenomenon was also verified in animal models, which indicated that interference with FAAH could effectively inhibit tumour growth in vivo." (PMID 36702852, 2023). "Functional tests confirmed that FAAH played an oncogene role in GC, and silencing FAAH could delay tumour growth, inhibit tumour metastasis, and promote cell apoptosis both in vitro and in vivo." (PMID 36702852, 2023). "We hypothesize that the inhibition of FAAH may be even more effective in vivo, where the tumor milieu is enriched with growth factors or cytokines and eCBs reach higher levels." (PMID 38139209, 2023). "In addition, qRT-PCR and western blot analysis of tumour tissues showed that silencing of FAAH inhibited the EMT of GC cells, indicating that tumour metastasis was inhibited." (PMID 36702852, 2023). "This hypothesis will need to be tested further, but is highly likely, based on current observations, that the levels and function of FAAH will also be altered in EC, as they are in other tumours." (PMID 31245282, 2019). "Further, we have investigated whether FAAH-IR is correlated with other pathogenetic and prognostic variables, such as the local tumour stage number and the immunoreactive score for phosphorylated epidermal growth factor receptor (pEGFR)." (PMID 20808855, 2010). "In consequence, in the present study, we have investigated the FAAH-IR in the tissue microarray used previously by us to characterise CB1IR in the tumour tissue, and undertaken studies using cultured cells to see if a known component of the tumour microenvironment can affect the FAAH activity." (PMID 20808855, 2010). "A case is made that the FAAH-IR is regulated by the tumour microenvironment, and a potential candidate molecule, IL-4, has been investigated in vitro, although contributions by other components of the tumour environment should certainly be considered." (PMID 20808855, 2010). "Notably, the tumors generated by FAAH-overexpressing MDA-MB-231 cells that reached the higher volumes were found to have silenced FAAH expression to some extent, as demonstrated by WB analysis, thus suggesting that the outcome (in terms of tumor growth) is dependent on FAAH expression." (PMID 37253733, 2023). "Interestingly, low tumor FAAH expression was linked to BC lung metastasis but not bone or brain metastasis." (PMID 37253733, 2023). "Moreover, patients with high FAAH expression in both the primary tumor and the LN metastasis (“FAAH high”) exhibited higher survival rates than those whose expression was either invariably low or decreased in the LN metastasis vs. the primary tumor (“FAAH low/decreased”)." (PMID 37253733, 2023). "Taken together, these results show that synergy of FAAH inhibitors with ferroptosis inducers significantly inhibits RCC tumor growth and metastasis, which demonstrates that targeting both FAAH and ferroptosis could be a promising therapeutic approach to treating RCC." (PMID 37024452, 2023). "These preclinical findings could prospectively help to analyse patients’ tumours pre-therapeutically in order to selectively find patients with COX-2-overexpressing tumours as inclusion criteria for successful tumour treatment with FAAH inhibitors." (PMID 35406541, 2022). "The high tumor FAAH-IR may serve as an indicator of poor prognosis." (PMID 36291926, 2022). "Furthermore, the protein levels of GGH and FAAH were significantly correlated in tumor tissues." (PMID 23374458, 2013).